GGNBP1 (gametogenetin binding protein 1 (pseudogene))
Description:
May be involved in spermatogenesis.
Gene: Transcribed unitary pseudogene on chromosome 6 (33,583,699 to 33,589,026, forward strand). Ensembl gene ENSG00000204188.
Subcellular location: Cytoplasm; Membrane; Golgi apparatus